CD4 (CD4 molecule)
Diseases named in the same sentence as CD4 in open-access papers (continued):
Sharing a sentence is not in itself a finding about the gene and the disease.
lupus nephritis (continued). "Our study showed that the expression level of serum IL-6 in cSLE correlated positively with the occurrence of lupus nephritis and degree of disease activity, and negatively with CD4+/CD8+, indicating a potential correlation between IL-6 and the pathogenesis of SLE." (PMID 33882880, 2021). "Anyway, target organ pathology in lupus nephritis, is inhibited by the TGFβ producing CD4+FoxP3+ Treg and CD8+FoxP3+ Treg cells induced by histone peptide epitope tolerance therapy, or by targeted nanoparticle therapy induced CD8+ Treg, which are quite different from the cytotoxic CD8 Treg." (PMID 33936042, 2021). "CD4+ T cells also infiltrate in kidney tissues and link to exacerbation of lupus nephritis." (PMID 33574820, 2020). "Finally, IL-17A-expressing CD4+Foxp3+ T cells were also detected in renal biopsy specimens of patients with active lupus nephritis." (PMID 32317002, 2020). "Finally, CD4+Foxp3+IL-17A+ cells were infiltrated into the renal biopsy specimens of patients with active lupus nephritis." (PMID 32317002, 2020). "CD4+IL-17A+ cells were detected mainly in the interstitial lesions of kidneys from both patients with lupus nephritis and those with IgA nephropathy, but the majority of the CD4+IL-17A+ cells also showed nuclear/cytoplasmic expression of Foxp3 in patients with lupus nephritis." (PMID 32317002, 2020). "In addition, DN T cells and CD4 T cells have been reported to infiltrate the kidneys of patients with lupus nephritis and produce the inflammatory cytokines interleukin-17 and interferon-γ." (PMID 31930150, 2019). "In this study, we could also find increased expression of PD-1 on peripheral CD4+ T-cells in lupus nephritis patients." (PMID 31331400, 2019). "Longitudinal data of patients with lupus nephritis further support the idea that CD4+CD25-Foxp3+ T cells might serve to recognize and monitor SLE patients with renal involvement." (PMID 24774748, 2014). "CD4+CD25-Foxp3+ T cells resemble a marker for lupus nephritis." (PMID 24774748, 2014). "CD4+ T cells compromise the majority of infiltrating cells in the kidneys of patients with active lupus nephritis and urinary concentrations of CD4+ T cells are correlated to severity of lupus nephritis." (PMID 24945254, 2014). "Indeed, CXCR3 bearing CD4+T cells infiltrating the inflamed kidneys have been detected in patients with active lupus nephritis." (PMID 24069401, 2013). "Less TNFSF4 may lead to induction of IL-10-producing CD4(+) type 1 regulatory T (Tr1) cells, while higher IL-10 was an intrarenal biomarker of disease activity in lupus nephritis." (PMID 23936824, 2013). "NZB/W is a murine model for lupus nephritis, and when these mice were treated with anti–PD-1–depleting Abs, the animals presented with less severe nephritis secondary to a reduction in the number of the CD4 T-cells that expressed PD-1 together with enhancement in the function of CD4 TREG." (PMID 35047501, 2021). "Indeed, kidney infiltration by CXCR3-expressing CD4+ T cells has also been detected in patients with active lupus nephritis, suggesting that the pathogenesis of the abdominal type is closely related to Tfh1 cells; refractory cases in particular merit further exploration." (PMID 29236760, 2017). "Long-term, continuous antigenic priming generated specific subsets of exhausted CD4 + and CD8 + T cells that promote functional T cell silencing of lupus nephritis." (PMID 38650001, 2024). "Umbelliferone reduced DN T cells, plasma cells, IFN-γ+CD4+ T cells, and T follicular helper cells (CD3+TCRβ+CD4+CXCR5+PD1+) and increased the percentage of Treg cells in lupus nephritis MRL/lpr mice." (PMID 39544933, 2024). "Cat S inhibitors were shown to suppress MHC class II-mediated CD4 T-cell and B-cell priming and thus improve SLE and lupus nephritis in a mouse model of SLE (MRL/lpr)." (PMID 36293172, 2022).
lupus nephritis (continued). "A Cat S inhibitor was shown to suppress MHC class II-mediated CD4 T-cell and B-cell priming and thus improve SLE and lupus nephritis in a mouse model of SLE (MRL/lpr)." (PMID 36293172, 2022). "On the other hand, blocking the ligand of PD1 leads to increased peripheral CD4+PD1+ T cells and accelerates lupus nephritis." (PMID 36430418, 2022). "It has been shown that monotherapy with metformin prevented the development of SLE through reduction in CD4+ T cell activation, expansion of germinal centre Tfh and B cells, serum antinuclear antibody (ANA) level and severity of lupus nephritis." (PMID 30959892, 2019). "This is of special interest as there is a link between increased CD4+CD25−FoxP3+ lymphocytes and lupus nephritis." (PMID 26525134, 2015). "In human patients with lupus nephritis, CXCR3 is similarly expressed on subpopulations of activated T cells and plasma cells as well as in a large proportion of CD4+ T cells that infiltrate the kidney." (PMID 24945254, 2014). "The significance of T cells in lupus nephritis was further confirmed by observing that the characteristics of SLE in NZB/NZW mice induced by IFN-α, such as anti-DNA Ab production and the development of nephritis, depend on the presence of CD4+ T cells." (PMID 39478861, 2024). "The percentages of IFN-γ-producing CD134+CD4+ T-cells were also significantly increased in HC as compared to patients without lupus nephritis (29.2 ± 19.4% vs. 15.0 ± 10.1%; p = 0.001)." (PMID 31331400, 2019). "The expression of OX40 on CD4+ T-lymphocytes and the serum level of OX40L may act as markers of lupus nephritis." (PMID 21245596, 2011). "As CD4+Foxp3+ nTreg cells had a minimal therapeutic effect on lupus nephritis, we were interested in exploring whether CD8+CD103+ iTreg have therapeutic effect on SLE/lupus nephritis." (PMID 29441062, 2018). "Furthermore, the frequency of CD4+CD45RO+CCR4+ lymphocytes correlated strongly with both ESR and CRP pointing to the potential proinflammatory role of these cells in lupus nephritis." (PMID 29670615, 2018). "When given to female MRL-Fas (lpr) (SLE) mice with lupus nephritis, RO5461111 significantly reduced the activation of spleen dendritic cells and the subsequent expansion and activation of CD4 T cells and CD4/CD8 double-negative T cells." (PMID 36293172, 2022). "We assessed the percentage of CD4+ T-lymphocytes expressing OX40 by flowcytometry, and serum OX40 ligand (OX40L) levels in 40 patients with SLE (20 with lupus nephritis and 20 without) and in 20 healthy controls." (PMID 21245596, 2011). "The percentage of CD4+ T-lymphocytes expressing OX40 was significantly higher in SLE patients than in controls, and in patients with lupus nephritis than in those without." (PMID 21245596, 2011). "Patients with and without active disease, as assessed by SLEDAI, and patients with and without lupus nephritis, proven by renal biopsy, were analysed for CD80 expression on CD4+CCR6+ cells." (PMID 20653937, 2010). "Although CXCR3 escape has not yet been convincingly demonstrated in human T cells, CD4+ T cells from patients with SLE exhibit female-biased overexpression of CXCR3, and CXCR3+ CD4+ T cells are enriched in the urine and inflamed kidneys of patients with active lupus nephritis." (PMID 35510951, 2022).
neutropenia (82 papers, 2011 to 2026). A decrease in the number of neutrophils found in the blood. "It was shown that patients with malignancy or HIV characterized by neutropenia, leukopenia, and low CD4+ lymphocyte count had a higher risk of A. radiobacter-caused IE." (PMID 39857828, 2025). "They typically have a low CD4 lymphocyte count, which is less than 100 cells/mm3, and are often associated with neutropenia." (PMID 41200601, 2025). "Neutropenia, glucocorticoids application, CD4+ T cell count less than 50 cells/μL are significant risk factors for invasive aspergillosis." (PMID 35130846, 2022). "Low level of CD4+ counts with the presence of additional risk factors like intravenous drug use and transient neutropenia should raise the suspicion of the development of mucormycosis in an individual." (PMID 36451988, 2022). "We demonstrated that patients who continue CPT have an increased risk of haematological abnormalities, mainly neutropenia, as well as a lower CD4 count increase under effective ART compared to those who stopped CPT." (PMID 30596666, 2018). "The use of pegIFNα 2a and CD4 cell count ≤350 cells/mL was associated with greater risk of neutropenia while carriers of the SOCS3 rs4969170 AG genotype had significantly lower risk of neutropenia." (PMID 23133602, 2012). "And in a 6-year longitudinal follow-up study of a cohort of patients living with HIV receiving TMP/SMX prophylaxis, the authors found that the only variable associated with neutropenia was a low baseline CD4 T-cell count, which determine the stage of HIV infection." (PMID 37167312, 2023). "In addition, an advanced HIV disease and a low CD4 count at ART initiation were also associated with a subsequent risk to develop a severe neutropenia." (PMID 28122041, 2017). "Neutropenia may be caused by adverse drug reactions or myelosuppressive drugs and it has been associated with low baseline CD4 count." (PMID 25209550, 2014). "Moreover, treatments for MM often cause even more immunosuppression: CD4 counts decrease after proteasome inhibitors (PIs) or monoclonal antibodies, whereas myelotoxicity, neutropenia, and decreased T-cell response, frequently follows therapy with immunomodulatory drugs (IMiDs)." (PMID 32923397, 2020). "Severe neutropenia in a low-level viremia and preserved CD4 T-helper cell (CD4) is uncommon and warrants evaluation for alternative etiologies." (PMID 41869130, 2026). "On multivariable analysis, factors associated with longer PFS included hypercalcaemia (p = 0.041), chemotherapy-induced neutropenia (p = 0.014) and CD4+/CD8- immunophenotype (p = 0.004)." (PMID 41914636, 2026). "Att-S74-T3Bo-vaccinated adult cattle developed significant (P<0.05) monocytosis, with concomitant neutropenia and CD4+ leukopenia, in peripheral blood early after vaccination." (PMID 37583702, 2023). "In CD4+ T-LGLL, neutropenia is uncommon, and similarly, in our cohort STAT5B mutated patients had normal ANC levels but increased lymphocyte and LGL counts." (PMID 35210405, 2022). "Unlike COVID-19, individuals infected with human immunodeficiency virus (HIV) who develop mucormycosis had underlying risk factors that comprised of parenteral drug use, corticosteroid use, CD4+ counts <50 cells/mm3 and transient neutropenia." (PMID 36451988, 2022). "• Improved neutropenia with increase in CD4+ T-lymphocyte counts. • Improved chemotaxis, phagocytosis, ROS production. • Reduction in apoptosis." (PMID 33777022, 2021). "All 86 patients associated antibody deficiency or memory B cell defect, while 24 of 86 (29%) presented multiple immune defect overlap, such as CD4+ T lymphocytopenia and innate immunity alterations (hypocomplementemia, neutropenia or low NK cells counts)." (PMID 34518828, 2021). "BMB indicated a numerically lower CD4+ to CD8+ T cells ratio in patients with irNeutropenia than in those with metamizole-induced neutropenia." (PMID 34746007, 2021).
neutropenia (continued). "The immunologic evaluation of these five patients with RD showed that one had neutropenia, one had decreased absolute lymphocytes, naïve CD4, and CD8 cells, two had decreased memory CD4 cells, and four had decreased memory CD19 B cells." (PMID 28623282, 2017). "The severity of lymphocytosis, consisting of elevated B cell and CD4+ T cell numbers, and neutropenia was most severe in patients with early onset HLH, and least severe in patients with no HLH (data not shown)." (PMID 28458669, 2017). "In a context where ZDV is still massively prescribed and most patients initiate ART at an advanced stage of the disease with low CD4 count, the implementation of the WHO recommendation will be crucial in order to reduce the risk of severe neutropenia." (PMID 28122041, 2017). "HIV infection is characterized by a reduction in total WCC, neutropenia and a particular reduction in CD4+ T cells but an increase in CD8+ T cells which is what we also observed in this study." (PMID 28382737, 2017). "Patient 5 had impaired expression of CD40 ligand on activated CD4+ T cells and also neutropenia, which are common findings in this PID." (PMID 24198970, 2013). "With respect to neutropenia we constructed a multivariate regression model which included the following variables: gender, type of pegIFNα prescribed, CD4 cell count stratified in two categories (≤350 and >350 cells/mL) and SOCS3 rs4969170 genotype." (PMID 23133602, 2012). "The trials overestimated DCR, CD3+ T cells, and CD3+ CD4+ T cells and underestimated neutropenia." (PMID 34122057, 2021). "We could confirm a slightly lower ratio of CD4+ to CD8+ T cells in ICI–met-induced neutropenia than in met-induced neutropenia, which indicates that CD8+ T cell infiltration could play a role in grade 4 ICI–met neutropenia." (PMID 34746007, 2021). "Although we could confirm a slightly lower ratio of CD4+ to CD8+ T cells in patients with ICI–met-induced neutropenia than in those with met-induced neutropenia, the number of patients in the study is small, and findings depend on the time of biopsy." (PMID 34746007, 2021). "To test whether Dnm2 wt/K562E mice display also signs of neutropenia, we evaluated blood samples of naïve Dnm2 wt/K562E mice and controls for CD4+ T cells, CD8+ T cells, B cells, neutrophils, inflammatory monocytes, macrophages and dendritic cells." (PMID 32129442, 2020). "According to one study, neutropenia could occur at a median CD4 count of 30 cells/mm3." (PMID 40558150, 2025). "Apart from zidovudine-containing regimens being associated with neutropenia due to their myelosuppressive actions, other cART regimens have generally been reported to resolve neutropenia in HIV-infected individuals with improvement in CD4+ T-lymphocyte counts following successful viral suppression." (PMID 33777022, 2021). "Due to high CD4 levels (more than 500/mm3) and a low viral load (<40 HIV copies/mL), HIV-induced neutropenia was excluded in our patient." (PMID 40558150, 2025). "There was significant publication bias in DCR, neutropenia, CD3+ T cells, and CD3+ CD4+ T cells, and the pooled results were robust; therefore, their quality was not downgraded." (PMID 34122057, 2021). "Incidence of severe neutropenia (ANC <750 cells/mm3) was estimated with 95% confidence interval (CI) according to age, gender, HIV clinic, hemoglobin, CD4 count, clinical stage, and ART duration." (PMID 28122041, 2017). "Thus, as expected, antibiotic therapy suppresses bone marrow, resulting in a decreased CD4:CD8 ratio, neutropenia and leukopenia." (PMID 33573218, 2021). "However, significant publication bias was found for DCR, neutropenia, CD3+ T cells, and CD3+ CD4+ T cells (p = 0.02, 95% CI 0.21 to 2.28; p = 0.03, 95% CI −2.24–−0.13; p = 0.01, 95% CI 3.94 to 16.11; and p = 0.001, 95% CI 4.04–13.58)." (PMID 34122057, 2021). "The main reasons for non-enrolment were low CD4 count, grade 3 or 4 neutropenia and failure to return after screening." (PMID 30596666, 2018).
neutropenia (continued). "The incidence was also significantly higher in patients exposed to an ART regimen containing ZDV (p <10−4), starting ART with a CD4 count <350 cells/mm3 (p <10−4), at clinical stage CDC 3 or WHO 4 (p <10−3) and in patients with neutropenia of grade 1 or 2 (p <10−4)." (PMID 28122041, 2017). "CMV was not considered ante mortem because Ganciclovir is not currently available at UTH, can cause leukopenia and neutropenia, and could be harmful in some HIV-infected children with a low CD4." (PMID 27363601, 2016). "In domestic cats, CD4+ T lymphocytes are progressively replaced by CD8+ cells but CD4+ cells show a very rapid decrease in late diseases stages, during which also leukopenia (neutropenia) is common, though not always observed." (PMID 34760956, 2021).
Kaposi's sarcoma (80 papers, 2004 to 2025). A malignant neoplasm characterized by a vascular proliferation which usually contains blunt endothelial cells. "The case underlines that though epidemic Kaposi sarcoma is often a disease of immunosuppressed people caused by retroviral infection, there is still the possibility in those with high CD4 counts despite viral load remains low." (PMID 40351467, 2025). "Opportunistic infections, such as Kaposi’s sarcoma (KS) and molluscum contagiosum (MC), are strongly associated with advanced immunosuppression, particularly in patients with low CD4 counts." (PMID 40161086, 2025). "Not surprisingly, mortality was higher in patients with CD4 counts of less than 200 cells per mL and in patients infected with human herpes virus 8, which is associated with the development of Kaposi sarcoma and primary effusion lymphoma in patients with low CD4 cell counts." (PMID 35544096, 2022). "Higher CD57+ CD4 T-cell frequencies have been associated with increased development of Kaposi's sarcoma, which may reflect defective antigen-specific responses." (PMID 27093273, 2016). "The other two deaths were from unknown causes though one woman had a CD4+ count less than 100 at the visit prior to her death and the other woman was reported to have Kaposi’s sarcoma at the time of her death." (PMID 25086834, 2014). "In PLHIV, administration of pomalidomide at 5 mg for 21 days for the treatment of Kaposi Sarcoma activated CD4+ and CD8+ T-cells, reduced T-cell senescence and expanded central memory CD4+ and CD8+ T-cells." (PMID 41232235, 2025). "In our analysis, the potential mediating effect of cellular immunodeficiency, inferred from the magnitude of the effect estimate change when adjusting for CD4 count, was largest for Kaposi sarcoma, conjunctival cancer, and non-Hodgkin lymphoma." (PMID 39736138, 2025). "The largest change after including CD4 count in the model was observed for Kaposi sarcoma and conjunctival cancer." (PMID 39736138, 2025). "Cerebral toxoplasmosis and cytomegalovirus manifested more frequently at lower CD4 counts (< 50 cells/μL: both 9.4%, 50–199 cells/μL: both 8.2%), while HSV ulcers and Kaposi’s sarcoma more frequently at higher CD4 counts of > 500 cells/μL (17.0% and 10.6%)." (PMID 38381307, 2024). "Published in the Journal of the National Cancer Institute, this study investigates the association between the CD4/CD8 ratio and the risk of Kaposi sarcoma in PWH." (PMID 38428854, 2024). "Kaposi sarcoma was presented by 16 (6.95%) patients in our study, with a mean CD4 count of 68 cells/mm3." (PMID 37581910, 2023). "As in IRIS-related Kaposi sarcoma, there is a temporal connection between CD4 count and progression of the Kaposi sarcoma." (PMID 35141174, 2022). "Recovery of immune responses, such as increased CD4 T cell counts with effective cART, clearly lowers the risk of AIDS-defining cancers such as Kaposi sarcoma and non-Hodgkin lymphoma." (PMID 35453518, 2022). "The incidence of Kaposi’s sarcoma (SK), strongly associated with HIV replication and CD4 immunosuppression, was greatly reduced." (PMID 34830857, 2021). "Accordingly, the risk of Kaposi’s sarcoma in HIV patients is inversely related to their CD4+ T cell count, although a few patients with relatively high CD4+ T cell count still had persistent Kaposi’s sarcoma." (PMID 32759845, 2020). "Most patients have cutaneous signs and a CD4 count of less than 100 at the time of diagnosis of gastric Kaposi’s sarcoma." (PMID 30867046, 2019). "We have detailed five conditions, with reference to the patients’ CD4 count – gastrointestinal tuberculosis, Kaposi’s sarcoma, small bowel lymphoma, cytomegalovirus colitis and anal carcinoma." (PMID 31754480, 2017). "Consistent with this aging CD4 T-cell phenotype, the cases were older in the Kaposi's sarcoma cohort, just as in this MRSA cohort." (PMID 27093273, 2016).